RHOT2 (ras homolog family member T2)
Description:
Atypical mitochondrial nucleoside-triphosphatase (NTPase) involved in mitochondrial trafficking. Probably involved in control of anterograde transport of mitochondria and their subcellular distribution. Can hydrolyze GTP (By similarity). Can hydrolyze ATP and UTP.
Synonyms: MIRO-2; ARHT2; C16orf39; MIRO2; RASL
Tractability: Small molecule: a structure with a bound ligand is known. Antibody: UniProt predicts a signal peptide or a membrane-spanning region. PROTAC: UniProt records ubiquitination sites on it; ubiquitination databases record sites on it; its protein half-life has been measured.
Target class: Enzyme; Hydrolase
Gene: Protein-coding gene on chromosome 16 (668,100 to 674,174, forward strand). Ensembl gene ENSG00000140983.
Subcellular location: Mitochondrion outer membrane
Subcellular location (Human Protein Atlas): Mitochondria
Pathways (Reactome):
Signal Transduction: RHOT2 GTPase cycle
Gene Ontology:
Molecular function: ATP hydrolysis activity; GDP binding; magnesium ion binding; protein binding; GTPase activity; calcium ion binding; GTP binding; ribonucleoside triphosphate phosphatase activity
Biological process: cellular homeostasis; mitochondrial outer membrane permeabilization; mitochondrion transport along microtubule; mitochondrion organization
Cellular component: membrane; mitochondrial outer membrane; mitochondrion
Genetic constraint (gnomAD): Loss-of-function variants: 89 observed, 80.04 expected, observed/expected ratio (o/e) 1.11, 90% interval 0.94 to 1.33. The synonymous counts are far from expectation, so gnomAD's model fits this gene poorly and the ratio says little. Missense variants: 988 observed, 833.11 expected, observed/expected ratio (o/e) 1.19, 90% interval 1.12 to 1.25. Synonymous variants: 501 observed, 363.85 expected, observed/expected ratio (o/e) 1.38, 90% interval 1.28 to 1.48.
Homologues: Orthologues: chimpanzee RHOT2 (99% identical), pig RHOT2 (86% identical), mouse Rhot2 (85% identical), macaque RHOT2 (84% identical), rat Rhot2 (80% identical), tropical clawed frog rhot2 (70% identical), zebrafish rhot2 (65% identical). Paralogues in human: RHOT1 (60% identical), RHOBTB2 (14% identical), RHOBTB1 (13% identical), CDC42 (12% identical), RHOU (12% identical), RAC1 (12% identical), RAC2 (12% identical), RHOV (12% identical), RHOJ (11% identical), RHOG (11% identical), RAC3 (11% identical), RHOQ (11% identical), and 10 more.
Diseases named in the same sentence as RHOT2 in open-access papers:
RHOT2 is named in the same sentence as 21 diseases in open-access papers, as found by Europe PMC text mining. Sharing a sentence is not in itself a finding about the gene and the disease. The quoted sentences say what the papers report.
bladder cancer (1 paper, 2025). "Although research on the function of RHOT2 in cancer is extremely limited at present, this study found that it can serve as a novel potential biomarker for bladder cancer, especially in relation to bladder cancer progression." (PMID 41427247, 2025). "This study identified five prognostic biomarker genes related to mitochondrial function and programmed cell death in bladder cancer (POLB, FASN, CASP9, VDAC2, and RHOT2) and preliminarily constructed a prognostic model based on these genes." (PMID 41427247, 2025). "In this study, a novel prognostic model for bladder cancer was constructed based on POLB, FASN, CASP9, VDAC2, and RHOT2, which provided preliminary references for the prognostic evaluation of bladder cancer and subsequent studies related to its diagnosis and treatment." (PMID 41427247, 2025).
colon cancer (1 paper, 2023). "(F) The RHOT2 protein expression in human colon cancer cells (SW480, HT29, HCT-116, RKO, DLD1, and LoVo) was measured by western blotting." (PMID 37158593, 2023). "Low expression level of RHOT2 markedly enhanced the migration ability of colon cancer cells (p<0.05)." (PMID 37158593, 2023). "The results of the transwell assay showed that the migration ability of colon cancer cells was significantly increased by si-RHOT2 (Student’s t-test, p<0.05)." (PMID 37158593, 2023). "RHOT2 silence significantly enhanced migration and invasion of colon cancer cells." (PMID 37158593, 2023). "Then, we investigated the effect of RHOT2 in the migration of colon cancer cells." (PMID 37158593, 2023). "However, whether RHOT2 could affect the LNM in colon cancer remains unclear." (PMID 37158593, 2023).
colorectal cancer (1 paper, 2023). A primary or metastatic malignant neoplasm that affects the colon or rectum. "(A) T1 colorectal cancer (CRC) samples from a set of 47 cases were used to verify the abundance of ABI1, ITPR2, RHOT2, ATAD2, and ISLR." (PMID 37158593, 2023).
gastric cancer (1 paper, 2023). A primary or metastatic malignant neoplasm involving the stomach. "Although the function of RHOT2 in cancer is still unclear, the expression of its paralog RHOT1 affects metastasis in a variety of tumors, including pancreatic cancer, gastric cancer, small cell lung cancer, etc.." (PMID 37158593, 2023).
Hypertension (1 paper, 2026). The presence of chronic increased pressure in the systemic arterial system. "In the PE rat model, downregulation of GCLM and SNAP23 and upregulation of RHOT2 were significantly correlated with clinical phenotypes such as hypertension and proteinuria, as well as changes in placental inflammatory factor levels (TNF-α, IL-1β, IL-6)." (PMID 41953137, 2026).
melanoma (1 paper, 2017). A malignant, usually aggressive tumor composed of atypical, neoplastic melanocytes. "The transcription levels of RhoBTB2 and RhoT2 were significantly lower in melanoma cells than in MC." (PMID 28404912, 2017).
tumor (8 papers, 2016 to 2025). "More analytical studies and experiments are needed in our future research to understand the specific role and mechanism of RHOT2 in the process of tumor metastasis." (PMID 37158593, 2023). "In addition, previous studies have found that Myc regulation of mitochondrial trafficking through RHOT1 and RHOT2 enables tumor cell motility and metastasis." (PMID 37158593, 2023). "In the database of UALCAN and LinkedOmics, RHOT2, and TCIRG1 were up-regulated in tumor than normal tissue and associated with tumor stage and OS significantly." (PMID 31681747, 2019). "RHOT2 and OGFR were significantly up-regulated in the GBM3 tumours (p < 0.05 and p < 0.01, respectively)." (PMID 30208958, 2018). "In our study, we found that abnormal expression of ASE of RHOT2 regulated by aberrant DDX39B could result in poor prognosis and tumor metastasis in patients with KIRC." (PMID 31681747, 2019). "For example, RHOT2 and OGFR were significantly up-regulated in the GBM3 tumours." (PMID 30208958, 2018).
cancer (7 papers, 2019 to 2025). A tumor composed of atypical neoplastic, often pleomorphic cells that invade other tissues. "On the other hand, RHOT2 is overall downregulated in cancer compared to normal tissue with exceptions being pancreatic adenocarcinoma, cholangio carcinoma and thymoma (as for Miro1)." (PMID 35959487, 2022).
neurodegenerative disease (1 paper, 2021). A disorder of the central nervous system characterized by gradual and progressive loss of neural tissue and neurologic function. "While the classic Rho GTPases play important roles in actin cytoskeletal regulation, Miro1 (RhoT1) and Miro2 (RhoT2) are atypical Rho-like GTPases involved in modulating mitochondrial homeostasis and apoptosis and are strongly implicated in neurodegenerative diseases such as PD." (PMID 34054432, 2021).
RHOT2 also shares sentences with these, for which no sentence is quoted: schizophrenia (2 papers); breast carcinoma (1); cardiac hypertrophy (1); infection (1); metastatic prostate carcinoma (1); neurological disease (1); pancreatic cancer (1); Parkinson (1); preeclampsia (1); prostate carcinoma (1); small cell lung carcinoma (1); Stroke (1).